CD5 (CD5 molecule)
Diseases named in the same sentence as CD5 in open-access papers (continued):
Sharing a sentence is not in itself a finding about the gene and the disease.
Autoimmunity (30 papers, 2009 to 2026). The occurrence of an immune reaction against the organism's own cells or tissues. "The increased expression of CD5 on T cells and B cells can prevent autoimmunity, and CD3E is positively associated with some T cells and macrophages." (PMID 36118358, 2022). "CD5, a transmembrane protein associated with T cells and found to be elevated in autoimmunity, was recently found to be significantly elevated in plasma of ASD subjects, and is associated with worsening severity of ASD." (PMID 30483058, 2018). "B1- and B2- B cells secrete immunoglobulin, but murine B1 subsets (CD11b+CD5+ and CD11b+CD5−) are implicated in innate defense against mucosal pathogens and autoimmunity development." (PMID 29273051, 2017). "CD5 plays a crucial role in autoimmunity and is a well-established genetic risk factor of developing RA." (PMID 25402503, 2014). "This dual role of CD5 and CD6 as both immunomodulatory and microbial PRR receptors is supported by pre-clinical models of infection, autoimmunity and cancer involving Cd5- and Cd6-deficient mouse lines, as well as infusion of wild-type mice with soluble CD5 and CD6 proteins." (PMID 36211446, 2022). "We speculate that the loss of CD5 in combination with risk variants for autoimmunity in the NOD genome cause a Crohn’s-like pathology." (PMID 35720357, 2022). "We further speculated that a genetic background prone to autoimmunity such as the NOD mouse could accentuate the consequences of CD5 deficiency." (PMID 35720357, 2022). "In contrast, in a 3′RR-deficient background tumors more often expressed the CD5 antigen (32% vs 12%, p = 0.05) that may serve to control autoimmunity and that is suspected to play a role in leukemic transformation." (PMID 25980500, 2015). "The development of therapeutic strategies to downregulate CD5+ B cells so as to mitigate ongoing autoimmunity and protect high risk individuals could be achieved if it turns out that autoimmune repertoires are concentrated in CD5+ B cells, the latter being readily identified by flow cytometry." (PMID 37373490, 2023). "CD5 was overexpressed in AS naïve B cells with CD5+ B cells being known to be involved in autoimmunity." (PMID 35634297, 2022). "As such, evolutionarily selected and/or functionally relevant polymorphisms in the CD5 and CD6 loci have been shown to impact a wide variety of immune-related disorders such as autoimmunity and cancer, often considered two sides of the same coin." (PMID 34070159, 2021). "Thus, CD5 dysregulation may be associated with autoimmunity." (PMID 34576267, 2021). "The interest of targeting CD5 in autoimmune disorders came first from mAb-mediated T cell suppression therapies." (PMID 33287301, 2020). "The highest surface levels of CD5 are found in mouse regulatory T (Treg; CD4+CD25+Foxp3+) and B cells (Breg or B10 cells; CD1d+CD5+), two IL-10-producing subsets involved in the prevention of autoimmunity." (PMID 33287301, 2020). "CD5+ B1a cells are the major producers of natural IgM and IgG3, aid in the control of infections, play a prominent role in autoimmunity, and produce high levels of IL-1044,45." (PMID 30643147, 2019). "Based on the differences in CD19+CD5+ B cells and serum IL-10 between patients and HC, supplementary assessments could be of value in clarifying their roles in autoimmunity." (PMID 35031055, 2022). "A similar result was found in a study on rheumatoid arthritis, which found that CD5+ B cells may be involved in autoimmunity." (PMID 35634297, 2022). "Using cytokines like IL-10, CD5 positive cells have a role in the prevention of autoimmunity." (PMID 33585004, 2020). "Thus, the CD5+ Breg subset is identified as an important regulator of autoimmunity and an inducer of immune tolerance." (PMID 31519970, 2019).
Autoimmunity (continued). "Thus, the genetic locus mediating suppression of autoimmunity in bicongenic mice is distinct from that leading to the marked expansion of CD5+ and NKT cells on NZB c4, with the exception of a minor additive effect on IgG anti-chromatin antibody production." (PMID 26964093, 2016). "Since we had previously shown that the CD5+ B cells in B6.NZBc4 mice have a regulatory function and produce IL-10, we questioned whether knockout of IL-10 could uncover autoimmunity." (PMID 26964093, 2016). "In addition, CD19+CD5+CD1dhighIL-10+ Bregs and CD1d+CD5+ B10 cells can also inhibit T cell immunity and regulate autoimmunity, infection and cancer." (PMID 25199644, 2014). "CD5+ B cells are reported to produce IL-10 with immunoregulatory property, which may explain a role of leptin in autoimmunity." (PMID 23343052, 2013). "Uptake of autoantigens by CD5+ B cells and subsequent presentation to T cells by cells that coexpress FasL would lead to selective elimination of the autoreactive T cells and protection from autoimmunity." (PMID 19706160, 2009). "The reduced functioning of CD19+CD24hiCD38hi and CD19+CD5+CD1dhi B cells seen here might therefore contribute not only to loss of Treg function with age, helping to promote autoimmunity, but also to the age-related increase in systemic inflammation." (PMID 23755918, 2013). "Here, we review available information on CD5 and CD6 as targets of natural selection as well as on the role of CD5 and CD6 variation in autoimmunity and cancer." (PMID 34070159, 2021). "Therefore, anti-CD5 mAbs may have a dual effect, by inducing both internalization of membrane-bound CD5 and T cell depletion, and their balance lead to increased or decreased autoimmunity." (PMID 33287301, 2020). "We show that the genetic locus leading to expansion of CD5+ B cell and NKT cell populations is localized to the mid 91 to 123 Mb region, whereas the predominant locus leading to suppression of autoimmunity is localized to the 123 to 151 Mb telomeric region." (PMID 26964093, 2016). "While CD5 deficiency did not to impact gut immunity in C57BL/6 mice, it did have a severe effect in the NOD strain that is pre-disposed to autoimmunity." (PMID 35720357, 2022). "Previous work has shown that an NZB-derived chromosome 4 interval spanning 32 to 151 Mb led to expansion of CD5+ B and Natural Killer T (NKT) cells, and could suppress autoimmunity when crossed with a lupus-prone mouse strain." (PMID 26964093, 2016). "Evidence from genetically-modified mouse models indicates that the absence or blockade of CD5- and CD6-mediated signals results in dysregulated immune responses, which may be deleterious or advantageous in some pathological conditions, such as infection, cancer or autoimmunity." (PMID 33287301, 2020). "However, transgenic TCR studies suggest the CD5-negative CD8+ T cells would also be more likely to mediate autoimmunity by reacting against self-peptides with low avidity TCR interactions and to skew the T cell repertoire through a selective advantage for homeostatic proliferation." (PMID 25237383, 2014). "To further explore CD5 function, we generated inducible CD5 knockdown (KD) mice in the nonobese diabetic (NOD) mouse strain prone to autoimmunity." (PMID 35720357, 2022).
thymic carcinoma (27 papers, 2007 to 2025). Thymic carcinoma (TC) is a type of thymic epithelial neoplasm characterized by a high malignant potential. "We report that CD5 immunoreactivity is significantly associated with the OS of patients with thymic carcinoma." (PMID 40242668, 2025). "CD117 and CD5 are well-known diagnostic markers for thymic carcinomas and are frequently used to separate thymomas from thymic squamous cell carcinomas." (PMID 26643918, 2015). "Overall, we find that CD5 immunoreactivity in thymic carcinoma is associated with longer OS." (PMID 40242668, 2025). "Previous studies have reported that 39% to 70% of thymic carcinomas are CD5 positive, with thresholds ranging from any degree of staining to strong or intermediate intensity staining in over 10% of tumor cells." (PMID 40242668, 2025). "Overall, 36% of thymic carcinomas in our study were positive for CD5 (i.e., ≥50% of tumor cell staining)." (PMID 40242668, 2025). "Tumor cells with vesicular nucleus, indistinct cell borders or squamoid nature mimic intrathyroid thymic carcinoma (formerly called CASTLE) but CD5 and CD117 markers are almost always positive." (PMID 38438897, 2024). "When exploring the possible regulators of CD5 expression in thymic carcinomas, we identified NFATC1 upregulation in the tumor." (PMID 38201543, 2023). "The specificity of CD117 and CD5 for thymic carcinoma versus thymoma was 100%, and the sensitivity of these markers for thymic carcinoma was 86% and 35%, respectively." (PMID 37190202, 2023). "Thymic carcinomas are positive for CD5 and CD117, whereas these immunohistochemical stains on cell block preparations are negative in thymomas." (PMID 37510144, 2023). "EZH2 used alone had 81% sensitivity for thymic carcinoma (using the ≥80% threshold), which was higher than the sensitivity of CD5 (35%) but lower than the sensitivity of CD117 (86%)." (PMID 37190202, 2023). "On the one hand, CD5 can be expressed in thymoma lymphocytes, but on the other hand, it has staining in the epithelial cells of thymic carcinomas." (PMID 37510144, 2023). "POU2F3 (≥10% hotspot staining), CD117, and CD5 showed 100% specificity for thymic carcinoma versus thymoma with 51%, 86%, and 35% sensitivity, respectively, for thymic carcinoma." (PMID 37190202, 2023). "In all other thymic carcinomas in which CD5 was tested, the percent of positive tumor cells was ≤10%." (PMID 35565429, 2022). "In the current report, we describe a case of CD5-positive squamous cell carcinoma with thymus-like features, and we postulate such cases should have a designated entity, such as intrasalivary thymic carcinoma analogically similar to thyroid tumors." (PMID 34807356, 2022). "Due to the morphological similarities with thymic carcinoma, CD5 and CD117 stainings were performed." (PMID 34807356, 2022). "CD5 is commonly expressed in the epithelial cells of thymic carcinomas, while in most thymomas, CD5 is seen exclusively in the lymphocytes." (PMID 35454918, 2022). "We found both markers to be useful in the prediction of thymic carcinomas if CD5 and/or CD117 were expressed in at least 50% or 10% of tumor cells, respectively, even though CD5 did not add any additional value to CD117." (PMID 35565429, 2022). "Immunohistochemically, positive reactivity for CD5 is a key feature for differentiating intrathyroid thymic carcinoma from undifferentiated thyroid carcinoma." (PMID 29885658, 2018). "On the other hand, several reports have described immunohistochemical examination of thymic carcinoma showing positive results for CD5, c-kit, or PAX8." (PMID 30446840, 2018). "Immunostaining against CD117, a transmembrane tyrosine kinase receptor, and against CD5, a member of the ancient scavenger receptor superfamily, is routinely performed to separate thymoma from thymic carcinoma." (PMID 26643918, 2015). "While CD117 is positive in approximately 85 % of thymic carcinomas, CD5 is positive in approximately 70 %, and about 60 % of cases show a CD117 and CD5 positive phenotype." (PMID 26643918, 2015).
thymic carcinoma (continued). "Our study supports the notion that CD5 immunohistochemistry may have utility as a novel prognostic marker for thymic carcinoma." (PMID 40242668, 2025). "The relatively low proportion of CD5-positive cases in our study is likely related to a high threshold for positivity, which was selected to allow 100% specificity for the distinction of thymic carcinoma versus thymoma." (PMID 40242668, 2025). "Moreover, the tumor displayed expression of squamous markers (p40 and p63) and markers of thymic carcinoma (CD5 and CD117)." (PMID 34807356, 2022). "CD5 expression is of limited value in the differential diagnosis of primary thymic epithelial neoplasms since both thymic carcinomas and thymomas may express CD5." (PMID 17498299, 2007). "Our study underscores the potential clinical relevance of variability in CD5 staining as a prognostic marker for thymic carcinoma, and the need for further investigation of mechanisms by which CD5 expression may impact the survival of patients with thymic carcinoma." (PMID 40242668, 2025). "The data suggest that CD5 is not a reliable diagnostic marker for primary thymic carcinomas since CD5 may be expressed also in thymomas." (PMID 17498299, 2007). "We aimed to determine the prognostic significance of CD5, CD117, EZH2, POU2F3, BAP1, and MTAP immunohistochemical staining in thymic carcinomas." (PMID 40242668, 2025). "Thymic carcinoma cells, for instance, more strongly express PAX8, CD5, and CD117 compared to lung cancer cells." (PMID 40506992, 2025). "CD5, CD117, EZH2, POU2F3, MTAP, and BAP1 have been proposed as useful markers for the distinction of thymic carcinoma from thymoma." (PMID 40242668, 2025). "For instance, thymic carcinoma cells more strongly express PAX8, CD5, and CD117 compared to lung cancer cells." (PMID 40506992, 2025). "We explored the relationship between CD5, CD117, EZH2, POU2F3, MTAP, and BAP1 immunoreactivity and the overall survival (OS) and progression-free survival (PFS) of patients with thymic carcinoma, using a cohort with diverse histologic subtypes." (PMID 40242668, 2025). "When distinguishing thymic carcinomas from lung primary squamous carcinomas, determining PAX8, CD5, and CD117 positivity in thymic carcinomas can be useful to distinguish thymic carcinomas from metastatic carcinomas." (PMID 37510144, 2023). "Whole slide sections of 37 thymic carcinomas, 23 type A thymomas, 13 type B3 thymomas, and 8 micronodular thymomas with lymphoid stroma (MNTLS) were immunostained for EZH2, POU2F3, CD117, CD5, TdT, BAP1, and MTAP." (PMID 37190202, 2023). "CD5 and CD117 have been previously proposed to aid in the distinction between B3 thymomas and thymic carcinomas." (PMID 35565429, 2022). "CD5 and CD117 (cKIT) are frequently positive in thymic carcinoma, with the sensitivity of each stain varying by subtype, but rarely positive in thymoma." (PMID 35454918, 2022). "Expression of GLUT1, CD5, and CD117 was significantly higher in thymic carcinomas than in thymomas (p < 0.001, each)." (PMID 35565429, 2022). "Bcl-2, calretinin, CD5, CD117, CEA, GLUT1, IGF-1R, mesothelin, MOC31, MUC1, and p21 were higher expressed in thymic carcinomas." (PMID 35565429, 2022). "Immunohistochemical staining for PAX8, CD5, c-KIT, TdT, and CD1a also demonstrated features that are characteristic to thymic carcinoma." (PMID 34328560, 2021). "Recently, differentiation related to the thymic/ultimobranchial sac has been postulated in the histogenesis of CMTC, given the co-expression of CK5 and CD5 in the morular component, together with positivity for CDX2 (recently detected in a subset of thymic carcinomas)." (PMID 40214777, 2025).
thymic carcinoma (continued). "The commonly used immunohistochemical markers CD5 and CD117 have only moderate sensitivity (33–73% and 65–85%, respectively) and imperfect specificity (72–100% and 85–100%, respectively) for the distinction of thymic carcinoma from thymoma." (PMID 37190202, 2023). "CD5 was negative in the poorly differentiated component, making a relation to intrathyroidal thymic carcinoma rather unlikely." (PMID 37249797, 2023). "Thymic carcinoma with intestinal metaplasia appeared to be a plausible diagnosis but negative CD5 staining was observed in our case and it was not known if mild intestinal metaplasia of the stomach was related to the anterior mediastinal tumor." (PMID 36482538, 2022). "However, immunohistochemical evaluation, including expression patterns of PAX8, CD5, c-KIT, TdT, and CD1a that are characteristic to thymic carcinoma, confirmed the diagnosis in our patient." (PMID 34328560, 2021). "However, CD5 did not add any value in the distinction between thymic carcinomas and thymomas, as all tumors that expressed CD5 in ≥50% of tumor cells also expressed CD117 in ≥10% of tumor cells." (PMID 35565429, 2022). "CD5 and CD117 immunohistochemistry should be considered in squamous cell carcinomas and undifferentiated carcinomas involving the salivary glands, especially when a distant primary tumor is not clinically evident and they display morphologic resemblance to thymic carcinoma." (PMID 34807356, 2022). "We postulate that CD5 and CD117 should be included in the immunohistochemical panel for squamous cell carcinomas and undifferentiated carcinomas of the major salivary glands with an unusual microscopic features, especially if they resemble thymic carcinomas morphologically." (PMID 34807356, 2022). "Micronodular thymic carcinoma with lymphoid stroma (MNCA) is considered as a malignant counterpart of MNT and exhibits a growth pattern similar to that of MNT but has histologic features reminiscent of thymic squamous cell carcinoma, such as cytologic atypia and CD5 and CD117 immunoexpression." (PMID 33819365, 2021). "Expression of CD5 in 50% or more tumor cells and CD117 in 10% or more tumor cells was only observed in a large subset of thymic carcinomas and not in any thymoma." (PMID 35565429, 2022). "Expression of CD5 in at least 50% of tumor cells and/or CD117 in at least 10% of tumor cells occurred in 10 (of 34, 29.4%) and 28 (of 35, 80%) thymic carcinomas, respectively, and in none of the thymomas." (PMID 35565429, 2022). "Other markers, such as CD5, CD117, and GLUT1, favor the diagnosis of thymic carcinoma rather than thymoma if they are expressed by neoplastic epithelial cells." (PMID 34439210, 2021). "Helpful cytologic and immunocytochemical features in making the diagnosis of thymic carcinoma are clear-cut cytological atypia, absence of immature lymphocytes (CD1a+, CD99+), and expression of CD5 and CD70 by neoplastic epithelial cells." (PMID 17498299, 2007). "Therefore, a low expression of CD5 and/or CD117 did not exclude the possibility of thymic carcinoma, but high expression supported this diagnosis." (PMID 35565429, 2022). "Here, we found that CD5 and CD117 were negative in thymic carcinoma." (PMID 28095872, 2017).